OR10G2 (olfactory receptor family 10 subfamily G member 2)
Description:
Odorant receptor.
Synonyms: OR14-41
Tractability: Antibody: UniProt places it where antibodies can reach, with medium confidence; UniProt predicts a signal peptide or a membrane-spanning region; its Gene Ontology location is reachable by antibodies, with medium confidence.
Gene: Protein-coding gene on chromosome 14 (21,633,836 to 21,634,940, reverse strand). Ensembl gene ENSG00000255582.
Subcellular location: Cell membrane
Pathways (Reactome):
Sensory Perception: Expression and translocation of olfactory receptors
Gene Ontology:
Molecular function: olfactory receptor activity; G protein-coupled receptor activity
Biological process: detection of chemical stimulus involved in sensory perception of smell; G protein-coupled receptor signaling pathway
Cellular component: plasma membrane; membrane
Genetic constraint (gnomAD): Loss-of-function variants: 0 observed, 0.68 expected, observed/expected ratio (o/e) 0, 90% interval 0 to 1.8. That is too few expected variants to judge how well the gene tolerates losing a copy. Missense variants: 396 observed, 382.05 expected, observed/expected ratio (o/e) 1.04, 90% interval 0.95 to 1.13. Synonymous variants: 147 observed, 162.21 expected, observed/expected ratio (o/e) 0.91, 90% interval 0.79 to 1.04.
Homologues: Orthologues: macaque OR10G2 (94% identical), guinea pig OR10G2 (90% identical), mouse Or10g1 (90% identical), rat Or10g1 (89% identical), mouse Or10g1b (88% identical), rat Or10g1b (87% identical). Paralogues in human: OR10G3 (73% identical), OR10G4 (57% identical), OR10G6 (57% identical), OR10G9 (57% identical), OR10G7 (56% identical), OR10G8 (55% identical), OR10S1 (55% identical), OR10D3 (50% identical), OR10C1 (45% identical), OR2W3 (44% identical), OR5V1 (43% identical), OR10A5 (43% identical), and 80 more.
Diseases named in the same sentence as OR10G2 in open-access papers:
OR10G2 is named in the same sentence as 2 diseases in open-access papers, as found by Europe PMC text mining. Sharing a sentence is not in itself a finding about the gene and the disease. The quoted sentences say what the papers report.
leukaemia (1 paper, 2017). "Nevertheless, OR10G2 is overexpressed in leukaemia cells and functions in cell proliferation in our study." (PMID 28387360, 2017). "Knockdown of OR10G2 inhibited the cell proliferation, suggesting that expression of ORs might have regulatory roles in leukaemia cell maintenance." (PMID 28387360, 2017).
cancer (1 paper, 2025). A tumor composed of atypical neoplastic, often pleomorphic cells that invade other tissues. "Among these were known cancer-testis antigens, previously reported TAAs, and novel candidates such as KCNU1 and OR10G2, which merit further functional validation." (PMID 41437377, 2025).